HES1 (hes family bHLH transcription factor 1)
Diseases named in the same sentence as HES1 in open-access papers (continued):
Sharing a sentence is not in itself a finding about the gene and the disease.
liver fibrosis (20 papers, 2012 to 2025). "Beyond its role in circadian regulation, NPAS2 has also been implicated in promoting liver fibrosis through its regulation of Hes1 expression." (PMID 41007411, 2025). "Hepatic HES1 mRNA was positively correlated with liver fibrosis in humans, and recombinant human HES1 overexpression repressed transactivation of the CEBPA gene." (PMID 38557493, 2024). "Utilising similar antibodies targeting IGF2BP3, Jag1, Notch1/3, and Hes1 as a therapeutic strategy in pre‐existing liver fibrosis models would enhance the translational value of these discoveries." (PMID 39113232, 2024). "In line with the CEBPA/OPN axis modulation on liver fibrosis, hepatocyte HES1 induction–enhanced liver fibrosis similarly induces hepatocyte-derived OPN release." (PMID 38557493, 2024). "NPAS2 increases liver fibrosis in hepatocellular carcinoma by direct transcriptional activation of Hes1 in hepatic stellate cells and induces glucose metabolism reprogramming and cell survival by transactivating CDC25A in liver cancer cells." (PMID 35880088, 2022). "Expressions of Notch2, Notch3, and Notch target gene Hes1 were significantly up-regulated during the development of hepatic fibrosis." (PMID 35883205, 2022). "NPAS2-deficient fibroblasts expedite skin wound healing and dermal collagen reconstruction, and NPAS2 promotes liver fibrosis via direct transcriptional activation of Hes1 in hepatic stellate cells." (PMID 34040522, 2021). "In liver fibrosis, TGFβ1 upregulates p-Smad2/3, Jagged1, Notch1 and Hes1, leading to trans-differentiation of hepatic stellate cells into myofibroblast cells." (PMID 32724452, 2020). "In the present study, we show Notch signaling to be highly activated in a rat model of liver fibrosis induced by carbon tetrachloride (CCl4), as indicated by increased expression of Jagged1, Notch3, and Hes1." (PMID 23056328, 2012). "These fibrinogens may foster HSCs activation by binding to integrin αvβ3/5 on HSCs’ membranes, suggesting the POFUT1/NOTCH/HES1/STAT3/fibrinogen axis as a novel therapeutic strategy of liver fibrosis." (PMID 40761743, 2025). "Although the expression of Notch1 and Notch4 decreased during the progression of hepatic fibrosis, the expression pattern of Hes1, a target gene downstream of Notch signaling, was similar to Notch3 and Jagged1, fluctuated with the progression and regression of hepatic fibrosis." (PMID 34239344, 2021). "The upregulated expression of Notch3 and Hes1 by activated HSCs and the increased synthesis of Jagged1 by neighboring hepatocytes and activated HSCs itself suggest that Notch signaling is activated in rats with liver fibrosis induced by CCl4." (PMID 23056328, 2012). "Experiments displayed that in the hepatic fibrosis mice model with POFUT1 knockout in LSECs, POFUT1 deficiency inhibited the KLF2-eNOS-sGC signaling axis, promoting injury-induced LSEC capillarization, while up-regulating the expression of fibrinogen in LSEC through the NOTCH/HES1/STAT3 pathway." (PMID 40761743, 2025). "In addition, we also observed that lnc-LFAR1 promotes hepatic fibrosis by activating Notch signaling in vitro and in vivo, as demonstrated by an increased expression of the Notch receptors, Notch2 and Notch3, and Notch target gene Hes1." (PMID 28747678, 2017). "Furthermore, Notch ligands (Dll1, Dll4, Jag1) and downstream molecule (Hes1) were also significantly induced in fibrotic mice versus olive-oil treated non-fibrotic control livers signifying the role of Notch pathway in liver fibrosis." (PMID 26658360, 2015). "We also found that Notch1/HES1 may be involved in sodium arsenite exposure-induced liver fibrosis and autophagy, and PTEN can regulate Notch1/HES1 to affect autophagy and fibrosis." (PMID 37505544, 2023). "Selective interruption of Hes1 could decrease the expression of α-SMA and Col1α2 and alleviate hepatic fibrosis." (PMID 35883205, 2022).
liver fibrosis (continued). "In this issue of the JCI, Yan and colleagues describe an ATF3/HES1/CEBPA/OPN pathway that links hepatocyte signals to fibrogenic activation of hepatic stellate cells and may provide new perspectives on therapeutic options for MASLD-induced liver fibrosis." (PMID 38557494, 2024).
lung cancer (18 papers, 2014 to 2025). A malignant neoplasm involving the lung. "Hes1 exhibits networked regulatory characteristics in lung cancer progression, and its potential as a therapeutic target urgently needs to be further explored." (PMID 40755759, 2025). "The ginsenoside Rg3 is able to trigger cell death in lung cancer cells by targeting the neurogenic locus notch homolog protein (Notch)/hairy and enhancer of split 1 (HES1) pathway and suppressing growth in NCI-H1650, H520, and H1963 cells." (PMID 41011591, 2025). "Accordingly, to describe Notch1-related effects in SCLC, it is essential to build thorough knowledge about Notch1 and its related protein expression (Hes1, c-Myc, and Jagged1) in various lung cancer cell lines." (PMID 40034926, 2024). "Collectively, these data suggest that the downregulation of HES1 contributes to the suppressive effect of SOX1 in lung cancer." (PMID 37190139, 2023). "To further investigate the role of HES1 expression in the carcinogenesis of lung cancer, we knocked down HES1 with HES1-shRNA and performed colony formation and invasion assays in H1299 cells." (PMID 37190139, 2023). "In this study, we demonstrated that the SOX1/HES1 axis contributes to cancer growth and invasion in lung cancer." (PMID 37190139, 2023). "Hes1 is a transcription factor that is downstream of Notch signaling, for which the pro-oncogenic activity in lung cancer has been established." (PMID 33960931, 2021). "The MR‐1/ITCH/NICD3/HES1 axis may be a promising therapeutic target in the progression of lung cancer." (PMID 38342606, 2024). "In summary, the interruption of MR‐1/ITCH/ NICD3/HES1 axis may be a new strategy for lung cancer treatment." (PMID 38342606, 2024). "Indeed, overexpression of SOX1 significantly repressed the expression of HES1 at both the mRNA and protein levels in two lung cancer cell lines." (PMID 37190139, 2023). "Similarly, PNO1/CRISPR/Cas9 inhibited the expression of Notch target genes Hes1 and Hey1 in lung cancer A549 and H460 cells." (PMID 36625087, 2023). "Interestingly, ST6GAL1 has been shown to regulate Notch1, Hes1, matrix metalloproteinases (MMPs) and vascular endothelial growth factor (VEGF) in lung cancer and altered α2-6 sialylation has been linked to lung cancer progression." (PMID 34290711, 2021). "Phenotypic rescue experiments further suggested that downregulation of HES1 contributes to the suppressive effect of SOX1 on colony formation and cell invasion in lung cancer." (PMID 37190139, 2023). "Restoration of SOX1 expression repressed HES1 via the direct binding of SOX1 to the HES1 promoter region and inhibited the malignant phenotype of lung cancer cells." (PMID 37190139, 2023). "Interestingly, downregulation of HES1 contributes to the suppressive effect of SOX1 on colony formation and cell invasion in lung cancer." (PMID 37190139, 2023). "We investigated HES1 expression in the putative stem-like cells, and found that its expression increased, suggesting that CD133+ cells display increased HES1 expression in lung cancer cells." (PMID 28881812, 2017). "An analysis of NOTCH1 and HES1 gene expression and Notch intracellular domain (NICD) nuclear translocation during DLK1 stimulation or depletion demonstrated that DLK1 could activate Notch signaling in lung cancer cells." (PMID 24621612, 2014).
prostate carcinoma (16 papers, 2010 to 2025). A carcinoma that arises from epithelial cells of the prostate gland. "Evaluation of the cellular localization of N3ICD following radiation exposure (5 Gy) identified a loss of expression in irradiated WT-22Rv1 prostate cancer cells, but maintained HES-1 expression." (PMID 31758038, 2019). "Although HES1 up-regulation is known to promote carcinogenesis, there are numerous reports demonstrating down regulation of HES1 in association with prostate cancer progression and in aggressive tumors." (PMID 25010594, 2014). "In Doc-resistant prostate cancer cells, HES1 is upregulated as part of a broader activation of the Notch signaling pathway, which also involves increased NOTCH2 and Hedgehog signaling." (PMID 40507238, 2025). "In accordance with this, the Notch pathway has been found activated in ERG-inducible LNCaP TMPRSS2:ERG (T2E) prostate cancer cells, as demonstrated by the upregulation of direct Notch pathway target genes such as HES1." (PMID 35954292, 2022). "An increased immunohistochemical expression of Snail1, Sumo1, TβRI, Hes1, and c-Jun was observed in aggressive prostate cancer tissues, consistent with their functional roles in tumorigenesis." (PMID 29228645, 2017). "As we have observed that Snail1 is critical for EMT regulation in prostate cancer, we performed immunohistochemical stainings for Snail1, Sumo1, TβRI, Hes1 and c-Jun, in prostate cancer tissues." (PMID 29228645, 2017). "Upon NOTCH3 knockdown, levels of HES1 remained steady in 22Rv1 cells but dropped in LnCaP cells, lending further support to the idea that HES1 responds to Notch signalling in prostate cancer cells." (PMID 25864518, 2015). "Combined with the RT-PCR and Western blot data, these studies suggest that overexpression of wild type Hes1 can reduce the expression of δ-catenin in prostate cancer cells." (PMID 21106062, 2010). "In this study, we demonstrated that Hes1 is a transcriptional repressor for δ-catenin and regulates δ-catenin expression in human prostate cancer cells and mouse models of prostate tumors by coordinating with transcription activator E2F1." (PMID 21106062, 2010). "Hes1 binds directly to the E-boxes on δ-catenin promoter and can reduce the expression of δ-catenin in prostate cancer cells." (PMID 21106062, 2010). "Hes1 is a target gene of Notch1 activation, which is believed to be critical for the development of prostate cancer." (PMID 21106062, 2010). "However, a study demonstrated that Hes1 can also activate osteogenic differentiation in prostate cancer bone metastatic cells." (PMID 39201457, 2024). "Increased positive stainings for Snail1, Sumo1, TβRI, Hes1, and c-Jun were found in the investigated prostate cancer tissues compared to the normal tissues, suggesting that TGFβ-promoted prostate cancer progression, involves increased expression of these EMT promoting factors." (PMID 29228645, 2017). "In this context, our data propose that the androgen-independent PC-3U cells, instead utilize sumoylated Snail1 to target TβRI to promote prostate cancer progression, as we have observed overexpression of Snail1, Sumo1, TβRI, Hes1, and c-Jun in prostate cancer specimens." (PMID 29228645, 2017). "Hes1 is a key transcriptional target in the notch signaling cascade and has also been implicated to play a crucial role in cancer metastasis, and EMT and elevated Jagged 1 expression has been reported in prostate cancer metastasis." (PMID 29228645, 2017). "While a single transcription activator or repressor less likely controls δ-catenin expression in prostate cancer cells, our current study supports the notion that Hes1 could negatively regulate the expression of δ-catenin in prostate cancer cells." (PMID 21106062, 2010). "δ-Catenin is upregulated in human prostate cancer, and Hes1 expression is altered in tumorigenesis." (PMID 21106062, 2010).
prostate carcinoma (continued). "However, the ability of Hes1 to inhibit the expression of δ-catenin in prostate cancer cells and the cooperation between Hes1 and other transcription factors for modulating δ-catenin expression in prostate development and tumorigenesis are still unclear." (PMID 21106062, 2010). "We then examined whether ectopic overexpression of Hes1 can act as a negative regulator of δ-catenin expression in prostate cancer cells." (PMID 21106062, 2010). "Because γ-secretase inhibitor DAPT reduced Hes1 level in prostate cancer cell lines, we sought to explore whether the γ-secretase inhibition-mediated increases in δ-catenin expression is accompanied by phenotypic changes with implications of neuroendocrine alterations." (PMID 21106062, 2010). "Notch signaling has been reported to become activated in prostate cancer cell lines exhibiting resistance to the clinically available AR inhibitor enzalutamide, as verified by the increased levels of cleaved NOTCH1, HES1 and c-MYC." (PMID 35954292, 2022). "The results were confirmed by other prostate cancer cohort (Multi-Institute, Nat Med 2016) from cBioportal which also showed the co-expression of SIRT6 and Hes1/Hey1." (PMID 33995674, 2021). "In prostate cancer CWR22-Rv1 and PC3 cell lines, which showed distinct δ-catenin overexpression, E2F1 and Hes1 expression pattern was altered." (PMID 21106062, 2010). "In prostate cancer, RASSF1A has been reported to be silenced in approximately 70% of patient tumors, which correlates with increased levels of the Notch downstream effector HES1." (PMID 35954292, 2022). "Diverse HEY1 and HES1 regulation by dihydrotestosterone was earlier observed in R1 castrate-resistant prostate cancer cell line, however the mechanism was not investigated in that study." (PMID 33167316, 2020). "In transgenic mouse models of prostate cancer, NE-10 prostate tumor from subcutaneous transplantation of 12T-10 tumor and CR2-TAg prostate, Notch-Hes1 signaling is down-regulated and may be responsible for the promotion of the neuroendocrine differentiation of prostate cancer cells." (PMID 21106062, 2010). "To test the hypothesis that Hes1 is a negative regulator of δ-catenin expression, we co-transfected Hes1 expression vectors (pcDNA-flag-WT-Hes1 or pcDNA-flag-DN-Hes1) and E2F1, together with δ-catenin-luciferase reporter vectors BK1 or BK5, into CWR22-Rv1 or PC3 human prostate carcinoma cell lines." (PMID 21106062, 2010).
hepatocellular carcinoma (14 papers, 2015 to 2025). A malignant tumor that arises from hepatocytes. "NOTCH2 activation causes HES1 overexpression, proliferation, immature morphology and invasion in an acute kidney injury model and hepatocellular carcinoma model." (PMID 37728427, 2023). "In hepatocellular carcinoma, overexpression of miR-760 downregulates the expression of Notch1 and Hes1, increasing the sensitivity of tumor cells to the chemotherapeutic drug doxorubicin." (PMID 40755759, 2025). "VPA treatment seems to induce the down-regulation of Notch activity via the suppression of its HES family bHLH transcription factor 1 (HES1) target gene, with augmenting p21 and p63 tumor suppressors in hepatocellular carcinoma cells." (PMID 31357442, 2019). "According to a previous research, miR-760 develops a drug-resistant function via impairing doxorubicin resistance in hepatocellular carcinoma by controlling Notch1/Hes1-PTEN/Akt signaling pathway." (PMID 31693728, 2019). "In hepatocellular carcinoma, hypomethylation of the promoter region of KK-LC-1 (a cancer/testis antigen) leads to its upregulation, which in turn promotes tumor progression by activating the Notch1/Hes1 signaling pathway." (PMID 40755759, 2025). "Complementary studies demonstrate that Notch/Hes1 inhibition reduces mTORC1 signaling in gastric cancer, while targeting the Hes1/PTEN/AKT/mTOR axis impairs hepatocellular carcinoma progression." (PMID 40755759, 2025). "In human hepatocellular carcinoma, Notch2 regulates the stemness of liver CSCs via upregulation of NRARP, HES1 and HES6." (PMID 30285832, 2018). "In hepatocellular carcinoma, POFUT1 overexpression induced an aberrant activation of NOTCH pathway switching on HES1, which in turn promoted migration and cell proliferation." (PMID 30380753, 2018). "Additionally, HES1 is a direct negative transcriptional regulator of CDKN1C in hepatocellular carcinoma cells." (PMID 36037042, 2022).
leukemia (14 papers, 2013 to 2025). A malignant (clonal) hematologic disorder, involving hematopoietic stem cells and characterized by the presence of primitive or atypical myeloid or lymphoid cells in the bone marrow and the blood. "The expression and function of Hes1 vary across different subtypes and developmental stages of leukemia." (PMID 40755759, 2025). "Another small molecule, perhexiline (a mitochondrial carnitine palmitoyltransferase-1 inhibitor), has also been found to possess Hes1 antagonist activity, demonstrating significant anti-tumor effects in leukemia models." (PMID 40755759, 2025). "The contradictory role of Hes1 in suppressing or promoting cancer in leukemia presents both a therapeutic challenge and a potential breakthrough." (PMID 40755759, 2025). "MiR-9 was found to suppress HES1 in acute myeloid leukemia (AML) to promote leukemia cell proliferation, and HES1 level was significantly downregulated in leukemic stem cells." (PMID 36674525, 2023). "Overexpression of the active form of Notch1 or Notch2 in the human KCL‐22 leukaemia cell line has been reported to inhibit proliferation, accompanied by an increase in Hes1 mRNA levels." (PMID 35122387, 2022). "Here, we observed that only leukemia cells expressing Hes1 and at least one Notch receptor cleaved/active form, as expected, were sensitive to in vitro treatment with GSIs." (PMID 26967055, 2016). "HES1 has a central role in NOTCH1-induced leukaemia suggesting that abrogation of HES1 activity in leukemia lymphoblasts could be exploited therapeutically." (PMID 37110858, 2023). "In SUP-T1 cells, apart from downregulation of the known BRD4 targets like Myc, Bcl-2, Bcl-XL, and Mcl-1, treatment with ARV-825 substantially decreased the expression of key molecules involved in leukemia persistence, such as HES1 (a direct target of Notch1), PI3K/AKT pathway proteins, and CD44." (PMID 35173274, 2022). "HES1 activation suppresses proliferation of leukemia cells in AML." (PMID 28261562, 2017). "Using RNA-Seq and RT-qPCR, we demonstrated that NOTCH1 and its respective target genes, such as HES1 and IGF1R, are upregulated and highly activated in MLLr leukemia cells." (PMID 37833915, 2023). "Mutated Notch1 co-occupies the distal enhancer region of the MYC promoting activation of NFkB signaling, Hes1, PTEN, and PI3K/Akt pathways in a feed-forward loop circuit that supports leukemia cell growth, proliferation, and self-renewal." (PMID 35173274, 2022). "In an in vitro leukemia model, two BMI1 inhibitors, PTC-209 and PRT-4165, down-regulating the expression of NOTCH1, HES1, and c-MYC, were able to block the leukemic cells growth, suggesting that the BMI1 inhibitors can be good candidates against leukemia." (PMID 30574454, 2018). "Next, we assessed the expression of ICN1 and HES1 in thymocytes and splenocytes from mice that displayed increased cellularity but have not yet developed overt symptoms of leukemia, namely lethargy, kyphosis and piloerection." (PMID 36765626, 2023). "Quantitative PCR analysis of Notch targets from total BM cells of leukemia mice revealed upregulations of Hes1, Deltex1 (Targets of Notch signaling) and IL7Rα compared to normal BM cells, in line with the reports that upregulation of IL7Ra is often observed in human T-ALL cells from patients." (PMID 33996794, 2021).